CHD7 (chromodomain helicase DNA binding protein 7)
Diseases named in the same sentence as CHD7 in open-access papers (continued):
Sharing a sentence is not in itself a finding about the gene and the disease.
CHARGE syndrome (continued). "Limb anomalies are often described as part of the clinical picture of CHD7 mutation and CHARGE syndrome." (PMID 34198905, 2021). "One of these proteins is CHD7 which was associated with CHARGE syndrome, the most well-established syndrome connected with the CHD family of proteins." (PMID 34828433, 2021). "Variants in CHD7 are mainly associated with CHARGE syndrome, presenting coloboma, heart defects, atresia of choanae, retarded growth, genital defects, and ear abnormalities as variable clinical traits." (PMID 34502334, 2021). "Heterozygous variants in CHD7 are the major cause of CHARGE syndrome, which is characterized by coloboma, heart defects, atresia of choanae, retardation of growth and/or development, as well as genital and ear anomalies." (PMID 33418956, 2021). "CHARGE syndrome is a CFW syndrome due to heterozygous pathogenic variants in the gene CHD7, a chromatin helicase protein." (PMID 33827624, 2021). "As haploinsufficiency of CHD7 is considered to be the pathogenic mechanism underlying CHARGE syndrome, we assume that a reduced amount of correctly spliced CHD7 transcript, resulting from the c.2095A>G variant, is disease-causing." (PMID 33418956, 2021). "Accordingly, mutated CHD7 is linked to CHARGE syndrome, which is characterized by several neuronal dysfunctions and by malformations of NC-derived/populated organs." (PMID 33869187, 2021). "Prominent among these mutations, haploinsufficiency of the chromatin remodeling enzyme CHD7 causes CHARGE syndrome, a multisystem disorder that includes a wide range of neurodevelopmental defects." (PMID 34588434, 2021). "Since most CHARGE syndrome patients show heterozygous mutation of the chromodomain helicase DNA binding protein 7 gene CHD7, animals with heterozygous Chd7 mutation are a popular research model." (PMID 34589045, 2021). "NGS confirmed pathogenic variants in CHD7 in P48 and P72; both patients were diagnosed with CHARGE syndrome (OMIM: 608892) and presented with a combination of cleft palate, heart malformations and immune abnormalities." (PMID 33777394, 2021). "Haploinsufficiency of the chromatin remodeling enzyme CHD7 causes CHARGE syndrome, a genetic disorder that affects the development of the cerebellum." (PMID 34588434, 2021). "Morbidity and mortality in CHARGE syndrome patients carrying loss-of-function mutations in CHD7 are frequently caused by heart defects, including OFT and atrioventricular septal defects." (PMID 33869187, 2021). "Mutations in the CHD7 cause CHARGE syndrome, that affect among other structures, the development of the ear." (PMID 34639189, 2021). "CHD7 is mutated in a congenital disorder called CHARGE syndrome 160, 161, but very little is known about CHD7 and cancer 162-164." (PMID 33391498, 2021). "We describe a familial case of CHARGE syndrome with significant intrafamilial clinical heterogeneity due to CHD7 gene mutation." (PMID 34297504, 2021). "A diagnosis of CHARGE syndrome is based on testing for the presence of a CHD7 gene mutation and/or a combination of the major and minor features." (PMID 34831689, 2021). "Mutations of the CHD7 gene are the major cause of CHARGE syndrome, which is characterized by coloboma of the eye, heart defects, atresia of the choanae, retardation of growth and development, genital abnormalities, and ear abnormalities." (PMID 33948885, 2021). "In humans, CHD7 haploinsufficiency causes CHARGE syndrome, a disorder affecting multiple organs including the ear." (PMID 34732824, 2021). "In their CHARGE syndrome patients, pathogenic missense mutations were mainly found in the middle of the CHD7 gene, where functional domains clustered." (PMID 35047002, 2021). "In humans, CHD7 haploinsufficiency is the major cause of CHARGE syndrome, a complex developmental disorder associated with growth retardation and defects of the eye, heart, genitals and the ear1,2." (PMID 34732824, 2021).
CHARGE syndrome (continued). "In contrast to the truncating CHD7 mutations that are observed typically in patients with CHARGE syndrome, patients with IHH harbor predominantly missense variants." (PMID 34563184, 2021). "Except for rhombencephalic anomalies and malformation of the mediastinal viscera, all CHARGE syndrome diagnostic items were noted in our CHH patients with CHD7 variants, and hearing loss (5/10; 50%) and high myopia (5/10; 50%) were the most common ones." (PMID 35047002, 2021). "For the EA ethnicity, six individuals have frameshift deletions at exon 9 for CHD7, the causative gene for CHARGE syndrome, where many patients also show ADHD behavior." (PMID 33671795, 2021). "39% of CHD7 mutation positive CHARGE syndrome patients were noted to have unilateral or bilateral CFW." (PMID 33827624, 2021). "One identifying factor is a mutation to the CHD7 gene, which has been identified as the cause of CHARGE syndrome." (PMID 34831689, 2021). "CHARGE syndrome results from variants within the chromodomain helicase DNA-binding protein 7 gene (CHD7) located on 8q12." (PMID 34198563, 2021). "Mice with heterozygous Chd7 mutations are an excellent model for CHARGE syndrome and, like humans, they exhibit SNHL3–6." (PMID 34732824, 2021). "It has been proposed that pathogenic CHD7 variant status is now a major criterion in CHARGE syndrome diagnoses." (PMID 34733806, 2021). "A subset of participants had also been referred for other diagnostic tests, including 22q11 deletion, Down syndrome, CHARGE syndrome (CHD7 sequencing), Noonan syndrome (PTPN11 sequencing) and other conditions, but with no definitive diagnoses." (PMID 32196547, 2020). "One case was diagnosed with CHD7 mutation conforming CHARGE syndrome (Coloboma, Heart defects, choanal Atresia, Retardation (of growth and/or development), Genitourinary malformation and Ear abnormalities)." (PMID 32100474, 2020). "Until 2004, mutations of chromodomain helicase DNA-binding protein 7 (CHD7) was found to be major cause for CHARGE syndrome and appear autosomal dominant inheritance pattern." (PMID 32625235, 2020). "Other genes, implicated in thymic organogenesis include FOXN1, associated with Nude SCID syndrome, PAX1, associated with Otofaciocervical Syndrome type 2, and CHD7, one of the genes implicated in CHARGE syndrome." (PMID 32922396, 2020). "Noteworthy is its interaction with CHD7, a gene mutated in CHARGE syndrome, which involves a clustering of congenital anomalies affecting several tissues." (PMID 32309624, 2020). "CHARGE syndrome occurs in approximately 1 in 8,500 to 10,000 new-borns and up-to-date more than 600 CHD7 variants in the AD form have been associated with the disorder." (PMID 32982993, 2020). "Heterozygous loss-of-function mutations in the gene encoding chromodomain helicase DNA-binding protein 7 (CHD7) are the major cause of CHARGE syndrome." (PMID 32267359, 2020). "De novo mutations in the gene encoding for Chromodomain Helicase DNA binding protein 7 (CHD7, #608892), for example, are a major cause of CHARGE syndrome." (PMID 32850830, 2020). "In humans, autosomal dominant mutations of CHD7 are associated with CHARGE syndrome, a constellation of congenital abnormalities including Coloboma, Heart defects, choanal Atresia, Retarded growth and development, Genital hypoplasia, and Ear anomalies." (PMID 33182738, 2020). "Mutations in CHD7 are predictive of Charge Syndrome (Congenital Hypogonadotropic Hypogonadism), a cause of pubertal defects in humans." (PMID 33250925, 2020). "CHD7 is the protein most frequently mutated in CHARGE syndrome, with the great majority of CHD7 mutations resulting in loss of function." (PMID 33188175, 2020).
CHARGE syndrome (continued). "Consistent with this, mutations in SEMA3E have been identified in patients with CHARGE syndrome and knockout of sema3e in zebrafish phenocopies chd7 knockout phenotype." (PMID 33182738, 2020). "Haploinsufficiency in a member of the chromodomain helicase DNA-binding (CHD) family of ATP-dependent chromatin remodeling enzymes (Chd7), causes CHARGE Syndrome, which presents with inner ear defects." (PMID 33015071, 2020). "CHARGE syndrome with chromodomain-helicase-DNA-binding protein 7 (CDH7) gene mutation is a genetic disease with an autosomal dominant gene." (PMID 33391964, 2020). "CHARGE syndrome is a complex disorder involving multiple congenital anomalies and is caused by heterozygous mutations in the CHD7 gene." (PMID 32267359, 2020). "CHARGE syndrome, a rare multiple congenital anomaly condition, is caused by haploinsufficiency of the chromatin remodeling protein gene CHD7 (Chromodomain helicase DNA binding protein 7)." (PMID 33060836, 2020). "Despite increasing number of CHD7 variants and associated features of CHARGE syndrome have been reported, the incidence of certain mutations and the effects on the phenotype remain to be illusive." (PMID 32625235, 2020). "CHARGE syndrome is a genetic disorder with highly variable phenotypes even within a family and results from mutations of CHD7 gene." (PMID 32625235, 2020). "CHARGE syndrome is a life-threatening disease caused by mutations of chromodomain helicase DNA-binding protein 7 gene (CHD7)." (PMID 32625235, 2020). "In this study, five patients were diagnosed as CHARGE syndrome with CHD7 mutations by whole exome sequencing." (PMID 32625235, 2020). "Mutations in the CHD7 gene are the leading cause of CHARGE syndrome, providing a link between colobomas seen in CHARGE syndrome to a direct mediator of apoptosis." (PMID 33505973, 2020). "We identified the CHARGE syndrome protein Chromodomain Helicase DNA-Binding Protein 7 (CHD7), whose deficiency causes excessive assembly of 53BP1 at chromatin surrounding DSBs." (PMID 33188175, 2020). "Chd7 mutant mice exhibited CHARGE syndrome in cardiac aspects while CHD7 mutations have been discovered in sporadic cases in congenital human heart defects." (PMID 32963551, 2020). "Heterozygous autosomal dominant loss-of-function variants in the CHD7 gene are the major causal factor of CHARGE syndrome, in addition to the fact that CHD7 variants have been also been reported in patients with isolated CHH." (PMID 32982993, 2020). "We aimed to investigate the phenotype spectrum of neonatal patients suspected to have CHARGE syndrome with pathogenic or likely pathogenic variants in the CHD7 gene." (PMID 31146700, 2019). "CHARGE syndrome and CHD7 pathogenic variants should be suspected in newborns who have feeding difficulty and one or more malformations." (PMID 31146700, 2019). "Mutations in the CHD7 gene cause CHARGE syndrome (Coloboma of the eye, Heart defects, Atresia of the choanae, Retardation of growth and development, Genital hypoplasia and Ear abnormalities), but have also been found in patients with isolated CHH." (PMID 30733481, 2019). "Chd7 is responsible for the spatiotemporally correct expression of several developmental genes and mutations, and Chd7 accounts for the majority of human CHARGE syndrome cases." (PMID 31159496, 2019). "CHARGE syndrome cases are predominantly caused by heterozygous loss-of-function pathogenic variants in the chromodomain helicase DNA-binding protein 7 (CHD7) gene." (PMID 31162046, 2019). "Heart defects are predominant features in CHARGE syndrome patients and patients with pathogenic CHD7 variants." (PMID 31146700, 2019).
CHARGE syndrome (continued). "The CHD7 gene is a member of the chromodomain helicase DNA-binding family and, when mutated, has been shown to be the cause of the CHARGE syndrome, a severe developmental human disorder." (PMID 30850678, 2019). "Based on a relatively unbiased neonatal cohort, we concluded that CHARGE syndrome and CHD7 gene variants should be suspected in newborns who have feeding difficulty, and one or more malformations." (PMID 31146700, 2019). "Mutation of the CHD7 gene has been reported to be linked to “CHARGE” syndrome in human embryo which “R” refers to retardation of growth and development when other abbreviation letters are ignorable." (PMID 31749588, 2019). "The chromodomain helicase DNA-binding protein 7 (CHD7) gene is the major cause of CHARGE syndrome and is inherited in an autosomal dominant manner." (PMID 31146700, 2019). "Proposed in 2016, pathogenic CHD7 variant status is now a major criterion in CHARGE syndrome diagnoses." (PMID 31146700, 2019). "For CHARGE syndrome patients with a CHD7 pathogenic variant, the relationship between genotype and phenotype is unclear." (PMID 31146700, 2019). "This study aims to reveal the consequences and the pathogenicity of a novel heterozygous splice site c.5535-1G > A variant in the CHD7 gene in a female patient with mild features of CHARGE syndrome." (PMID 31315586, 2019). "CHARGE syndrome is an autosomal dominant malformation disorder caused by heterozygous loss of function mutations in the chromatin remodeler CHD7, which has been estimated to occur in 1:10,000 births worldwide." (PMID 29945602, 2018). "Heterozygous loss-of-function mutations in CHD7 are known to cause CHARGE syndrome in children (OMIM: 214800)." (PMID 30359267, 2018). "Heterozygous null mutations in CHD7, the gene encoding chromodomain helicase DNA binding protein 7, cause CHARGE syndrome, a disorder characterized in part by global sensory deficits including malformation and dysfunction of the ear." (PMID 30459807, 2018). "The patient’s phenotype and the family segregation pattern indicated this CHD7 mutation as a de novo mutation resulting in CHARGE syndrome (OMIM 214800)." (PMID 29458409, 2018). "As her features were consistent with phenotypes described in the literature for CHD7‐associated CHARGE syndrome, we felt that the variant was the causal." (PMID 29368431, 2018). "Humans with heterozygous pathogenic variants in CHD7 exhibit CHARGE syndrome, characterized by hearing loss and inner ear dysplasia, including abnormalities of the semicircular canals and Mondini malformations." (PMID 30459807, 2018). "Due to 97% of CHD7 mutations are de novo, CHARGE syndrome usually occurs as a new autosomal dominant condition, with variable expressivity and no family history." (PMID 30317490, 2018). "A novel splice site mutation in CHD7 was found in this patient reclassifying him as having CHARGE syndrome." (PMID 29434620, 2018). "Here, we presented a novel monoallelic frameshift mutation of CHD7, NM_017780.3 (c.4656dupT) in a Chinese patient with CHARGE syndrome." (PMID 29945602, 2018). "Certainly, pSAD-based minigenes represented valuable tools to functionally check variants of the SERPINA1 (severe alpha-1 antitrypsin deficiency) and CHD7 (Charge Syndrome) genes." (PMID 29881398, 2018). "Mutations in CHD7 have been shown to be a major cause of CHARGE syndrome, which presents many symptoms and features common to other syndromes making its diagnosis difficult." (PMID 29434620, 2018). "Pathogenic mutations were identified in three families (n = 3/33, 9.1%), including mutations in DNAH11, RAF1 and CHD7, which were associated with primary ciliary dyskinesia, Noonan syndrome, and CHARGE syndrome, respectively." (PMID 30359267, 2018). "In HGMD Professional 2017.2, 757 CHD7 mutations have been reported in CHARGE syndrome, 96 of them being splice mutations." (PMID 29434620, 2018). "Mutations in Chd7 gene are responsible for CHARGE syndrome, in which, heart and vascular system are impaired." (PMID 28152519, 2017).
CHARGE syndrome (continued). "While homozygous loss-of-function mutation of Chd7 is embryonic lethal at E10.5, heterozygous mutant mice are viable but show phenotypes closely mimicking CHARGE syndrome." (PMID 29033785, 2017). "More recently, it was shown that CHD7 proteins containing mutations that are associated with the human developmental disorder CHARGE syndrome have highly impaired remodeling activity in vitro compared with WT CHD7." (PMID 28330902, 2017). "The CHD7 gene encodes a chromatin-remodeling factor and is mutant in CHARGE syndrome, which has the constellation of Colobomata, Heart Anomalies, choanal Atresia, Retardation, Genital and Ear anomalies." (PMID 29280744, 2017). "Similar to CHD7 mutations in the CHARGE syndrome, these mutations in human cancers were also distributed throughout the entire coding region of CHD7 genes (Basson and van Ravenswaaij‐Arts, 2015)." (PMID 28649742, 2017). "In humans, mutation of CHD8 is associated with autism spectrum disorders (ASDs), and haploinsufficient mutations of CHD7 are strongly associated with CHARGE syndrome and Kallmann syndrome, two severe multisystem disorders." (PMID 28330902, 2017). "Structural MRI analysis of a small cohort of CHARGE syndrome patients with CHD7 mutations identified cerebellar vermis hypoplasia in 35% of patients, with evidence for abnormal foliation in 25% of patients." (PMID 29168327, 2017). "We herein demonstrate that the chromodomain helicase DNA-binding protein 7 (Chd7), frequently associated with CHARGE syndrome, is indispensable for normal cerebellar development." (PMID 28317875, 2017). "Mutations in the chromatin modifier Chd7 have been associated with CHARGE syndrome and other developmental disorders." (PMID 28317875, 2017). "Two decades later, de novo mutations in the CHD7 gene were identified in CHARGE syndrome patients, which turn out to be the major cause of this disease." (PMID 29033785, 2017). "Over 90% of patients with clinically typical CHARGE syndrome have heterozygous mutations in the CHD7 gene." (PMID 29033785, 2017). "A diagnosis of CHARGE syndrome was made in three boys, with mutations in CHD7 found in two of these boys." (PMID 28938747, 2017). "CHARGE syndrome has been associated with mutations in the gene encoding the ATP-dependent chromatin remodeler CHD7." (PMID 28165338, 2017). "Most of CHD7 mutations in CHARGE syndrome patients result in truncated CHD7 protein that apparently lost its ATPase and chromatin remodeling activities." (PMID 29033785, 2017). "Most CHD7 mutations in patients with CHARGE syndrome are nonsense mutations or frameshift deletions; missense mutations of CHD7 are associated with milder CHARGE symptoms." (PMID 28649742, 2017). "In vitro nucleosome remodeling assays have confirmed the ability of CHD7 to translocate nucleosomes along a chromatin template and demonstrated a loss or reduction in this activity in CHARGE syndrome–associated CHD7 mutants." (PMID 28165338, 2017). "Mutations in CHD7 cause CHARGE syndrome, a complex developmental syndrome defined by a constellation of birth defects, which include coloboma, heart defects, atresia of the choanae, retarded growth and development, and genital and ear abnormalities." (PMID 28165338, 2017). "CHARGE syndrome is caused by heterozygous mutations in the chromatin remodeler, CHD7, and is characterized by a set of malformations that, on clinical grounds, were historically postulated to arise from defects in neural crest formation during embryogenesis." (PMID 29179815, 2017). "CHD7 can translocate nucleosomes in an in vitro assay, an activity compromised by CHD7 mutations associated with CHARGE syndrome." (PMID 28330902, 2017). "Most CHD7 mutations found in CHARGE syndrome affect ATP‐dependent chromatin remodeling (Basson and van Ravenswaaij‐Arts, 2015)." (PMID 28649742, 2017). "Several CHD7 mutations identified in CHARGE syndrome were found to affect its nucleosome remodeling activity." (PMID 26188466, 2016).